BRCA2 (BRCA2 DNA repair associated)
Diseases named in the same sentence as BRCA2 in open-access papers (continued):
Sharing a sentence is not in itself a finding about the gene and the disease.
cancer (continued). "BRCA1 and BRCA2 (BRCA1/2) are the most commonly studied genes in Caucasian cancer patients, although there are few studies on Asians." (PMID 40904409, 2025). "This is especially relevant in therapeutic settings, such as platinum-based therapies commonly used for BRCA2-mutant cancer, which induce replication stress." (PMID 41162355, 2025). "This large proportion of potentially preventable cancers further supports BRCA1/BRCA2 screening before age 40 years in populations with high carrier rates." (PMID 40116830, 2025). "Pathogenic germline mutations in BRCA1 and BRCA2 are known to cause hereditary breast and ovarian cancer syndrome (HBOC), leading to cancer development at a relatively young age." (PMID 40249378, 2025). "Olaparib, a PARP inhibitor, has received FDA approval for the treatment and maintenance of several cancers, particularly those with a germline BRCA1 or BRCA2 mutation, including HER2-negative metastatic breast cancer." (PMID 40723906, 2025). "A prominent finding of our study is that cancer penetrance in carriers of BRCA2 PVs is significantly modified by cancer‐specific PGS." (PMID 40462315, 2025). "In particular, breast cancer gene 1 (BRCA1) and breast cancer gene 2 (BRCA2), which are critical in human cancer, also influence the development and progression of canine tumors." (PMID 40004231, 2025). "The identification of novel BRCA2 transcripts underscores the complexity of its regulation in cancer." (PMID 40640493, 2025). "A retrospective case–control study used data on 150,962 women tested with a multigene hereditary cancer panel to evaluate an 86-SNV PRS in BRCA1, BRCA2, CHEK2, ATM, and PALB2 P/LP variant carriers." (PMID 39858629, 2025). "Although insignificant, BRCA2 carriers were more concerned about the possibility of getting cancer one day (p = 0.66) and about developing cancer (p = 0.27) but they worry less about their family members developing cancer (p = 0.28)." (PMID 40390061, 2025). "When near-complete and complete responses were combined, the difference between BRCA2- and BRCA1-associated cancers remained significant [9/15 (60%) vs. 12/48 (25%), Fisher’s exact test, two-tailed, P = 0.02]." (PMID 40547808, 2025). "We found that 15 KIF family proteins have various connections with 11 of the ACMG cancer-associated genes, including BRCA1 and BRCA2." (PMID 39409999, 2024). "BRCA2 c.156_157insAlu accounted 46% of BRCA PVs in the Portuguese cancer cohort in our current study, much higher than the originally reported one-fourth, 33.6% or 37.9%." (PMID 38671360, 2024). "Genomic expression data published in The Cancer Genome Atlas (TGCA) show that POLQ is significantly overexpressed in cancer when BRCA1 or BRCA2 are altered." (PMID 38666816, 2024). "Simulated uptake of BRRM and RRSO in unaffected BRCA1 and BRCA2 was in line with uptake observed in a familial cancer clinic population and the Lifepool cohort." (PMID 39766065, 2024). "These inhibitors work well in cancers that have flaws in homologous recombination (HR) DNA repair, especially those caused by BRCA1 or BRCA2 mutations." (PMID 39001539, 2024).
cancer (continued). "Concerning PARP inhibitors, current policy for most cancers allows reimbursement only when a BRCA1 or BRCA2 alteration has been confirmed." (PMID 38872153, 2024). "The roles of BRCA1, BRCA2, and ATR in cancer susceptibility, cyclins and cell cycle regulation, BRCA1-dependent Ub ligase activity, polyadenylation of mRNA, and Sonic Hedgehog receptor Ptc1 regulating cell cycle were the most enriched pathways in BioCarta." (PMID 39765633, 2024). "The development of PARP inhibitors like Olaparib has significantly improved the treatment of cancers with DDR defects (e.g., BRCA1 or BRCA2 mutations) based on synthetic lethality." (PMID 39372203, 2024). "Recent advances in cancer research have shed light on the HR-independent functions of BRCA2, such as epigenetic regulation and transcription control, albeit not in the PDAC context." (PMID 39595558, 2024). "With regards to FANCD2, the O/E for cancer risk and more specifically BC risk, were similar to that of BRCA2 (FANCD1), an established high-risk BC gene." (PMID 38814507, 2024). "An analysis using an expanded set of cancer-related genes (COSMIC Cancer Gene Census), produced similar results with no other recurrently mutated gene significantly enriched in BRCA1/BRCA2 mutant cancers." (PMID 39198848, 2024). "The application of the concept was first validated clinically in cancers with BRCA1 and BRCA2 mutations leading to HR repair deficiency." (PMID 39156700, 2024). "Loss of CSB leads to re-sensitization of SMARCAL1-depleted BRCA2-deficient cells to chemodrugs, underscoring a role of CSB in targeted cancer therapy." (PMID 38416570, 2024). "Our DNA-seq analysis of 76,639 pan-cancer samples identified 31 DDR/FA signaling genes, with ataxia-telangiectasia mutated (ATM) showing the highest mutation rate at 5%, followed by BRCA2/FANCD1 at 4%." (PMID 39421870, 2024). "Also, whether both copies of BRCA2 are inactivated in cancers from mutation carriers is proving to be quite important because sensitivity to targeted therapies, like platinum compounds or poly-ADP ribose polymerase (PARP) inhibitors, only occurs when that second wild-type copy of BRCA2 is lost." (PMID 39711301, 2024). "Various cancer predisposition genes, including BRCA1, BRCA2, and p16/CDKN2A, have already been identified in high-risk pedigrees." (PMID 38894738, 2024). "Functionally uncharacterized cancer mutants BRCA2 E2474*, BRCA2 R2502Lfs*24 and BRCA2 N2553Tfs*95, with truncations upstream of NLS1, satisfying criteria PM1 and PM4, are annotated as ‘BRCA2 mutants (NLS)’ set candidates." (PMID 38713862, 2024). "In our study with cancer genome panel testing, BRCA2 with germline PVs (gPVs) and/or somatic PVs (sPVs) was detected in 395 (395/2361; 16.73%) patients with advanced-stage/metastatic GC." (PMID 39590127, 2024). "In another study of 13,129 cancer-free Chinese individuals, the BRCA1 and BRCA2 mutation rates were 0.2% and 0.4%, respectively." (PMID 39272924, 2024). "In the non‐cancer cohort, 25/492 (5%) participants carried 17 unique P/LP variants in ATM, BRCA2, BRIP1, CHEK2, MUTYH, NBN, and PMS2 genes." (PMID 38308423, 2024). "Cancer cells bearing deficiencies in HR, such as those with mutations in BRCA1 or BRCA2 genes, tend to be vulnerable to DNA-damaging agents like platinum-based drugs." (PMID 39001539, 2024). "Our analysis suggests that undergoing both RRSO and RRM is the most effective and cost-effective option for BRCA1, BRCA2, and PALB2 PV carriers, with younger surgery ages for those with higher cancer risk preventing more cancers." (PMID 38334999, 2024). "Homologous recombination deficiency (HRD) occurs in approximately half of the cancers; it is caused by germline mutations of BRCA1 or BRCA2 in at least 15%." (PMID 38175731, 2024).
cancer (continued). "It produces syndromes associated with a moderate risk of cancer due to a limited hyper-recombination accompanied by a lack of cell cycle control (e.g., category 2 syndromes like BRCA1 and BRCA2 mutations)." (PMID 39335159, 2024). "Breast Cancer Type 1 Susceptibility Protein (BRCA1) and Breast Cancer Type 2 Susceptibility Protein (BRCA2) have a crucial function in DNA damage repair via homologous recombination pathway." (PMID 38582911, 2024). "The advent of poly(ADP-ribose) polymerase inhibitors (PARPi) has revolutionized the treatment landscape for cancers harboring homologous recombination (HR) deficiencies, particularly those resulting from BRCA1 and BRCA2 mutations." (PMID 38789420, 2024). "BRCA2 is considered a tumor suppressor gene because its participation in DNA repair limits the possibility of cancer transformation." (PMID 38892180, 2024). "According to cancer genome panel testing, BRCA2 with gPV and/or sPV was detected in 395 (395/2361; 16.73%) of 2361 patients with advanced-stage/metastatic GC." (PMID 39590127, 2024). "BRCA1/BRCA2/BRCA carrier cancer risks were specified by 47% (37/79) of websites (58%, 26/45 UKOs; 19%, 3/16 JCOs; 44%, 8/18 GTPs)." (PMID 39001386, 2024). "Given that the CRISPR screens were performed separately for BRCA1−/− and BRCA2−/− backgrounds, we reanalyzed human cancer genomic data separating BRCA1 and BRCA2 tumors in OV and ER+ BC to identify candidate drivers for each gene individually." (PMID 39198848, 2024). "Some kind of cancers, such as breast and ovarian cancers, have mutations in the BRCA1 or BRCA2 genes that compromise their homologous recombination ability." (PMID 38327984, 2024). "Here, we report 9 out of 24 patients with non-contributory family history, harboring germline heterozygous deleterious mutation in well-known cancer predisposing genes (CHEK2, RAD51C, BRCA2, FANCA, RET, FH, and BAP1)." (PMID 38700789, 2024). "Inhibition of PARP1 in cancer therapy is a recently adopted strategy to treat cancers where DNA repair is defective, such as HBOC caused predominantly by pathogenic variants in BRCA1 or BRCA2." (PMID 39062754, 2024). "As long as one wild-type copy of BRCA2 remains, cells seem to be pretty normal in their capacity to carry out the cancer-preventing functions of BRCA2 that preserve genome stability." (PMID 39711301, 2024). "The most common cancer in relatives was BC (36.4% for BRCA1 and 44.5% for BRCA2 PV‐carriers), which was also the first cause of death from cancer in relatives (24.5% and 21%); however, this data was missing for around 20% of women." (PMID 39624976, 2024). "For example, ATM and BRCA2/FANCD1 had the highest mutated rate in only 5 out of 15 and 4 out of 15 cancer types, respectively." (PMID 39421870, 2024). "The key neighbor genes, which formed neighbor-cancer gene pair in two-hop module (such as ROCK2-BRCA2 pair in BRCA2 gene module), provide new insights to understand tumorigenesis and drug combination strategy." (PMID 39013885, 2024). "This compromised DNA repair capacity predisposes cells to malignant transformation or apoptosis, highlighting the critical role of BRCA1 and BRCA2 in DNA damage repair in maintaining cellular health and preventing cancer." (PMID 39199310, 2024). "This is likely due to the presence of BRCA2, PTEN, and MDM2 mutations, which make this type of cancer responsive to platinum-based chemotherapy." (PMID 39201255, 2024). "Previous successes in cancer therapy have exploited the synthetic lethality of cancer-specific cellular deficiencies, for example PARP inhibition in BRCA2-deficient cancer cells." (PMID 39506153, 2024). "Although most sporadic and hereditary BRCA1 cancers carry the TNBC phenotype (ER−, PR−, HER2−), the majority of hereditary BRCA2 cancers are of a luminal type (HR+, HER2-)." (PMID 38893102, 2024).
cancer (continued). "These early guidelines did not set specific thresholds for genetic testing but, emphasised the importance of testing high risk individuals with cancer to open the possibility of testing for BRCA1, BRCA2 and Lynch syndrome genes." (PMID 38478259, 2024). "In 2017, he was awarded the Basser Global Prize for his groundbreaking research uncovering how BRCA2 suppresses cancer by protecting genome integrity." (PMID 39711301, 2024). "We next explored the effect of ANM-associated genes on cancer outcomes, replicating previously reported associations with PTVs in BRCA2, CHEK2 and PALB2 and cancer outcomes in male and female subjects." (PMID 39261734, 2024). "In contrast, other DNA damage response and repair genes, including BRCA1, BRCA2, ATM, BRIP, POLQ, and CDK12, were significantly more often mutated in CDX2-suppressed cancers." (PMID 39452477, 2024). "Cancer cells can survive a single alteration in BRCA1 or BRCA2 and subsequently adopt a backup DNA repair pathway." (PMID 38398147, 2024). "Positive RNA–RNA correlations were widespread between POLQ and multiple cancer driver genes most notably BRCA2." (PMID 39166898, 2024). "We gathered 352 distinct germline variants (127 for BRCA1 and 225 for BRCA2) from 2,080 Han Chinese healthy individuals and 522 patients with BRCA mutation-related cancer." (PMID 38566028, 2024). "Mutations in the tumor-suppressor genes BRCA1 and BRCA2 resulting in BRCA1/2 deficiency are frequently identified in breast, ovarian, prostate, pancreatic, and other cancers." (PMID 39007266, 2024). "There were 172 women (mean [SD] age, 47.1 [11.7] years) treated with BCT who had pathogenic BRCA variants identified using the Clinical Cancer Genetics Program Database; 92 (53.5%) had BRCA1 variants and 80 (46.5%) had BRCA2 variants." (PMID 38916888, 2024). "Studies have shown that hypoxia-induced by anti-angiogenic therapy inhibits HR repair by suppressing the expression of key factors such as BRCA1 and BRCA2, leading to a deficiency in DDR and rendering BRCA1/2 wild-type cancer cells sensitive to PARPi." (PMID 39156700, 2024). "Patients carrying variants of uncertain significance expressed greater concerns about developing another cancer compared to those who had BRCA1 and BRCA2 wild type or pathogenic variants." (PMID 38500651, 2024). "The chemotherapeutic agent CX-5461, or pidnarulex, has been fast-tracked by the United States Food and Drug Administration for early-stage clinical studies of BRCA1-, BRCA2- and PALB2-mutated cancers." (PMID 38036782, 2024). "Meanwhile, NCCN_cancer targets were mainly composed of ERBB2 amplification (40%), BRCA2 pathogenic mutations (40%), and CDKN2A oncogenic mutations (20%)." (PMID 38661052, 2024). "Inactivation of RAD52 in homologous-recombination-deficient BRCA1- or BRCA2-defective cells is synthetically lethal, and aberrant expression of RAD52 is associated with poor cancer prognosis." (PMID 38658755, 2024). "Literature review underscored BRCA2's role in DNA damage repair and its critical function in cancer chemoresistance." (PMID 38773866, 2024).
cancer (continued). "CRISPR-based gene editing can also be used to repair genetic mutations that cause cancer, such as in the case of inherited forms of cancer caused by BRCA1 and BRCA2 mutations." (PMID 38195537, 2024). "We therefore performed a proximity biotinylation study that identified products of several known cancer genes that are associated with USP44, including a novel interaction between BRCA2 and USP44." (PMID 39767807, 2024). "Patients with germline mutations of DNA damage repair genes (BRCA1, BRCA2, or NTHL1) had a later evolutionary onset of dissemination than patients with triple-proficient cancers (P = 0.03 by Wilcoxon’s test)." (PMID 38175731, 2024). "This is expected given the central role of these proteins and pathways in cancer, the long IDRs of BRCA1 and BRCA2 and the large number of disease-associated mutations found in these regions." (PMID 39009827, 2024). "It is important to emphasize how the use of the multigenic panel, including 27 genes associated with hereditary cancers, allowed us to increase the detection rate of unaffected individuals with mutations in genes beyond BRCA1 and BRCA2." (PMID 39001389, 2024). "Clinical trials evaluating BRCA mutation status have demonstrated enhanced responses to platinum‐based chemotherapies, underscoring the pivotal role of BRCA2 in cancer treatment." (PMID 38773866, 2024). "Classifying genetic variants of uncertain significance (VUS) in cancer genes such as BRCA1 and BRCA2 by PARP inhibitor sensitivity would result in clinically actionable, patient-specific information." (PMID 37488236, 2024). "SL interactions are exploited in cancer treatment e.g. BRCA1/BRCA2 and PARP, where targeting an SL partner of a cancer-specific mutation can selectively eliminate cancer cells." (PMID 39435285, 2024). "For unaffected women, earliest age of family cancer diagnosis was significantly associated with PV status only for BRCA1 (OR 2.34, 95% CI 2.13–2.56) and BRCA2 (OR 1.25, 95% CI 1.16–1.35)." (PMID 37084156, 2023). "The common pathway of DNA damage sensing and cell replication control is shared with other proteins, such as BRCA1, PLAB2, BRCA2, and RAD51, whose genes are implied in cancer susceptibility conditions." (PMID 37509701, 2023). "A theoretical interest in PARP inhibition in ATM-mutated cancers stems from the involvement of the kinase in the same HR repair pathway as BRCA1 and BRCA2." (PMID 36975505, 2023). "Women with BRCA1 mutations are more likely to develop malignant pathology at a younger age, so one would expect an increase in occult cancers at the time of RRSO compared with BRCA2 carriers." (PMID 36837501, 2023). "One of the applications of NGS is inherited cancer testing by targeted NGS panels focusing on high‐penetrant/high‐risk mutated genes, such as BRCA1 and BRCA2." (PMID 37092543, 2023). "Mutations in key DNA repair genes, such as breast cancer 1 (BRCA1) and/or breast cancer 2 (BRCA2), induce genomic instability and promote tumorigenesis." (PMID 36902170, 2023). "Following an isolated retroperitoneal nodal recurrence, given the expected enhanced sensitivity to radiotherapy in BRCA2 mutant cancers, the patient underwent imaging-guided radiotherapy leading to long-lasting complete tumor remission." (PMID 36998040, 2023). "Analysis of high-risk cancer pedigrees identified in this powerful Utah resource previously provided the identification of BRCA1 and BRCA2, and CDKN2A, which remain the most common cancer predisposition genes to be identified." (PMID 37046747, 2023). "These, in turn, cause DNA strand breaks that disrupt DNA repair mechanisms and contribute to the genomic instability that drives cancer development, as seen in BRCA1 and BRCA2 mutations." (PMID 38067328, 2023).